BRCA1 (BRCA1 DNA repair associated)
Diseases named in the same sentence as BRCA1 in open-access papers (continued):
Sharing a sentence is not in itself a finding about the gene and the disease.
breast cancer (continued). "Breast carcinoma in the CSbbph-low group that corresponds to a CSddrm-low immunophenotype has a 95% 10-year rate, but the ten-year DSS rate of breast carcinoma with a BRCA1+/BRCA2+/PARP1+/γH2AX+ immunophenotype was 35%." (PMID 27643881, 2016). "Similarly, we previously reported on the prognostic significance of the combined expression patterns of the DDR molecules PARP1, γH2AX, BRCA1, and BRCA2 designated as CSbbph (combined score for the BRCA1, BRCA2, PARP1, and γH2AX) in breast carcinoma." (PMID 27643881, 2016). "Moreover, our previous study demonstrated that the combined expression pattern of PARP1, γH2AX, BRCA1, and BRCA2 is very helpful in the prediction of the prognosis of breast carcinoma." (PMID 27643881, 2016). "Whereas miR-155 was found to be repressed by deacetylation of H2A and H3 through a mechanism mediated by BRCA1 in breast cancer, such reports are lacking in lung cancer, even though BRCA1 is not that unimportant in lung cancer." (PMID 25743773, 2015). "Unfortunately, no animal's survived BRCA1 knockout long enough to determine any biological effects on breast cancer." (PMID 26379698, 2015). "The role of BRCA1 and BRCA2 in breast cancer progression and prognosis is well documented." (PMID 26258011, 2015). "We showed that the median age at diagnosis for TNBC patients with either BRCA1 or BRCA2 is younger than for non-TNBC patients (38 vs 46 for BRCA1 and 38.5 vs 48 for BRCA2), suggesting that BRCA1- and BRCA2-associated breast cancer is most likely early-onset." (PMID 26221963, 2015). "Today, it is established that BRCA1- and BRCA2-associated breast cancers are not phenotypically identical." (PMID 25925750, 2015). "In conclusion, in contrast to basal-like BRCA1 mutated breast cancers, no apparent specific somatic copy number aberration (CNA) profile for CHEK2*1100delC breast cancers was found." (PMID 26553136, 2015). "CLDN1 expression was previously found to be relatively low in triple negative breast cancer, but was highly expressed in BRCA1-related breast cancer and high-grade basal-like breast cancer." (PMID 26067567, 2015). "Further studies will also be needed to determine whether such BRCA1/BRCA2 mutational differences contribute directly or indirectly to the biological differences between BRCA1 and BRCA2 breast cancers." (PMID 25699710, 2015). "For example, we did not have information on BRCA1 and BRCA2 mutations, family history of breast cancer, and occupations before or after military service." (PMID 26376727, 2015). "This suggests that breast cancer CSC in humans and pigs are regulated in a similar manner by BRCA1." (PMID 26379698, 2015). "In general, our study indicated that the frequency of BRCA1 promoter methylation was statistically significant elevated in breast cancers compared with non-cancer controls (OR = 3.15, 95%CI 1.97–5.03, P < 0.001)." (PMID 26643130, 2015). "In a prospective study of 2,483 women with BRCA1 or BRCA2 mutations, no breast cancers were diagnosed in the women who underwent RRM during 3 years of prospective follow-up." (PMID 26557407, 2015). "Expanding WGS to ClinVar genes also identified a LoF mutation in the tumor suppressor gene DLEC1 in a BRCA1-mutant patient (BRCA1.73); the function of the encoded DLEC1 protein is not well defined but has been found to be lost in breast cancer." (PMID 26023681, 2015). "Quantitative polymerase chain reaction (PCR) and bisulfite sequencing PCR were respectively used to detect expression differences of BRCA1 mRNA and BRCA1 methylation in the 49 cancerous and paired non-cancerous samples from patients with breast cancer." (PMID 25789047, 2015). "The dysregulated SOS1 and SPRY1 induced by BRCA1 knockdown might therefore inactivate the Ras/MAPK pathway, which has an important role in breast cancer." (PMID 26039571, 2015).
breast cancer (continued). "It has been shown that BRCA1-related breast cancers have low expression of estrogen receptor (ER), progesterone receptor (PR) and human epidermal growth factor receptor (HER2/neu) as compared with sporadic breast cancers." (PMID 26496879, 2015). "Compared to DMBA Only-treated controls, irrespective of genotype, mammary tumours from mice treated with DMBA + ROSI trended toward increased PPARγ expression accompanied by increased BRCA1 expression (p = 0.09)." (PMID 25889730, 2015). "BRCA1 mRNA expression levels in the 49 breast cancer tissues were lower than those in the paired non-cancerous tissues." (PMID 25789047, 2015). "The molecular basis of increased recruitment of the BRCA1 mRNAa to ribosomes in breast cancer cells treated by EPA is not known at the present time." (PMID 25762631, 2015). "For example, IMA does not identify BRCA1 hypermethylation in breast cancer while MethylMix identifies BRCA1 hypermethylation in 8% of breast cancer patients." (PMID 25631659, 2015). "We observed the frequency of BRCA1 promoter methylation was statistically significant higher in breast cancers than non-cancer controls." (PMID 26643130, 2015). "Given that both half-sisters previously had uninformative (negative) BRCA1 and BRCA2 testing, a multigene panel that included other breast cancer predisposition genes was offered and completed." (PMID 26484312, 2015). "As expected, CLT induced expression of BRCA1 in both MCF-7 and HME-Rho C breast cancer cells." (PMID 25762631, 2015). "Second, it’s noteworthy that there were no related articles for the prevalence of BRCA1 promoter methylation in breast cancers in the African population among our eligible literatures." (PMID 26643130, 2015). "This study reports that rat mammary tumors induced with the AhR-agonist 7,12-dimethyl-benzo(a)anthracene (DMBA) had augmented CpG methylation of the Brca-1 gene; higher expression of Ahr, Cyp1b, and proliferation markers (Cdk4, Ccnd1); and diminished expression of BRCA-1 and ERα." (PMID 26715507, 2015). "This work also opens the possibility of utilizing non-dietary agents that cause phosphorylation of eIF2α for prevention and/or treatment of breast cancers that express high level of BRCA1 mRNA but not protein." (PMID 25762631, 2015). "Immuno-positivity of TRα was not significantly different when BRCA1 mutant and sporadic breast cancers were compared though THRA mRNA expression was induced in HCC3153." (PMID 26029931, 2015). "Furthermore, rare germline genomic duplications and deletions have been shown to disrupt high-penetrance tumor suppressor genes, such as the BRCA1 and BRCA2 genes, in breast cancer patients, and have been demonstrated to aggregate within families." (PMID 26152678, 2015). "Methylation-sensitive high-resolution melting was used to screen promoter methylation in a panel of 13 genes reported as methylated in breast cancer (RASSF1A, TWIST1, APC, WIF1, MGMT, MAL, CDH13, RARβ, BRCA1, CDH1, CDKN2A, TP73, and GSTP1) in 29 tumour pairs (16 ipsilateral and 13 contralateral)." (PMID 26452468, 2015). "35.0% (35/100) breast cancer tissues were positive for PARP1 expression in the nuclei; 34% (34/100) breast cancer tissues were positive for BRCA1 expression in both the nuclei and cytoplasm, 33% (33/100) breast cancer tissues were positive for BRCA2 expression in both the nuclei and cytoplasm." (PMID 25865228, 2015). "Firstly, BRCA1 expression at the mRNA level was detected in paired cancerous and non-cancerous tissue of sporadic breast cancer." (PMID 25789047, 2015). "Therefore, it suggested that normal breast tissues had a lower prevalence of BRCA1 methylation than benign and malignant breast tissues, which also implied that the methylation of BRCA1 gene promoter may play a certain role in the initiation of breast carcinoma." (PMID 26643130, 2015).
breast cancer (continued). "Given that PCGT methylation is a hallmark of almost all cancers and that a BRCA1 defect in normal non-neoplastic cells is likely to silence PCGTs and compromise cell differentiation, we posited that our BRCA1 DNAme signature may be able to predict sporadic breast cancer." (PMID 25067956, 2014). "BRCA1-related breast cancers tend to also be higher grade, hormone receptor-negative, and HER-2-negative, or “triple negative”, and also frequently express a basal phenotype." (PMID 24579064, 2014). "For instance, 1,25(OH)2D3 interacts with the 53BP1 protein to eliminate invasive breast cancer cells lacking BRCA1." (PMID 24982636, 2014). "Since the 13q34 amplification and/or CUL4A overexpression is more frequent in BRCA1-associated and basal-like primary breast tumors we selected the BRCA1-null HCC1937 and the 13q34 amplified MDAMB157 cell lines to further characterize CUL4A function in breast cancer progression." (PMID 24870930, 2014). "BRCA1 dysfunction can tilt this delicate balance resulting in ER-α positive or ER-α negative breast cancer." (PMID 23873416, 2014). "In addition, we report the differential expression of another fifteen cancer-related genes, other than BRCA1, in the WBC from the carriers and breast cancer patients." (PMID 25403427, 2014). "Since BRCA1 has been found to be methylated in WBC genomic DNA, we hypothesized that other breast cancer related genes may also be epigenetically affected." (PMID 25403427, 2014). "Among the eleven compounds confirmed in our secondary screen that exhibit strong synergy with PARPi in killing breast cancers irrespective of their BRCA1 status, four can inhibit NF-κB activity (lestaurtinib, bortezomib, ouabain, and digitoxin)." (PMID 24962108, 2014). "Our study shows the presence of genome instability in the genomes of non-breast cells in the BRCA1+ familial breast cancer family." (PMID 24884718, 2014). "Our main analyses of breast tumor features included up to 3,929 BRCA1 mutation carriers, 2,273 BRCA2 mutation carriers, and 42,623 assumed BRCA1 and BRCA2 mutation-negative breast cancer cases." (PMID 25857409, 2014). "It is important to note that not all breast cancer patients with BRCA mutations responded to PARP inhibition and a substantial number of patients with advanced BRCA1-mutant cancers are resistant to these agents." (PMID 24795863, 2014). "Initial evidence suggests that BRCA1 is a key negative modulator of PRC2 and that loss of BRCA1 inhibits stem cell differentiation and enhances an aggressive breast cancer phenotype by affecting PRC2 function." (PMID 25067956, 2014). "A recent report demonstrated that BRCA1 polyubiquitinates G2/M cell cycle proteins including cyclin B and Cdc25C and targets these proteins to be degraded by the ubiquitin-proteasome pathway in an APC/C-independent manner in breast cancer cells." (PMID 24704793, 2014). "The present study reports the case of a patient with MEN1-associated tumors and breast cancer, in which we identified germline mutations in MEN1, but not in BRCA1/2." (PMID 24959251, 2014). "Female BRCA1/2 carriers were identified from the Manchester genetic database, and included in the study regardless of breast cancer status or age." (PMID 25274085, 2014). "This chromosomal gain was present in only 28.6% of the BRCA1 non-mutated TNBC, 26.7% of the unscreened TNBC, 13.6% of the luminal B, 19.0% of the HER2+ and 0% of the luminal A breast cancers." (PMID 25416589, 2014). "Patients that lost BRCA1 expression often had more advanced breast cancer and were tumor node metastasis stage III positive, lymph node positive and overexpressed c-Myc." (PMID 25051360, 2014).
breast cancer (continued). "Methylation of BRCA1 promoter leads to BRCA1 gene silencing and there is no preclinical data to suggest that the biological therapeutic sequelae of BRCA1 silencing depends on the subtype of breast cancer." (PMID 25177489, 2014). "Reporters were transfected into various breast cancer cell lines and assayed for differences in luciferase gene expression as a surrogate for BRCA1 expression in the presence or absence of the BRCA1-3’UTR-variant." (PMID 24915755, 2014). "Some previous studies presented an association of RAD51 variant allele 135C with an elevated breast cancer risk only in BRCA2 mutation carrier, but not in BRCA1 mutation carriers or non-carriers or unselected populations." (PMID 24040396, 2013). "In contrast, in the genetically engineered non-metastatic BrCa1 mammary cancer model (on a mixed mouse strain), the expanded myeloid cells did not upregulate CD79a (CD79-11)." (PMID 24146823, 2013). "We propose that rare VUS affecting phosphorylation may be a novel and important mechanism for which BRCA1 and BRCA2 functions are disrupted in breast cancer." (PMID 23704879, 2013). "BRCA1 and BRCA2 are the two major genes, but explain only about 20% of inherited breast cancers." (PMID 24139550, 2013). "The defect of (pT371)TRF1 in forming IR-induced foci was also detected in the breast cancer HCC1937 cells expressing truncated BRCA1 lacking its C-terminal BRCT domain." (PMID 23997120, 2013). "We evaluated whether 191 BRCA1 and 43 BRCA2 VUS from the Breast Cancer Information Core (BIC) database can functionally alter the consensus phosphorylation motifs and abolish kinase recognition and binding to sites known to be phosphorylated in vivo." (PMID 23704879, 2013). "Characteristics of BRCA1-2 (n = 26), BRCAX (n = 58) and sporadic (n = 77) breast cancers." (PMID 23326384, 2013). "BRCA2-related tumours usually express estrogen and progesterone receptors and tend to have similar features to sporadic breast cancers, unlike BRCA1-related cancers." (PMID 23586058, 2013). "The youngest affected woman, not known to carry a mutation in BRCA1 or BRCA2, from 747 multiple-case breast cancer families participating in kConFab were selected for PALB2 mutation screening." (PMID 23448497, 2013). "Among them, the transcription factor, SOX11, a progenitor cell and lineage regulator of nonmammary cell types, is found highly expressed in some Brca1-/- mammary tumors." (PMID 23506684, 2013). "In this study, we show that BRCA1 activates the Notch pathway in both non-tumorigenic and breast cancer cells, in addition to primary breast tumours, through transcriptional upregulation of Notch receptors and ligands." (PMID 23863842, 2013). "General classification and within-subtype classification of BRCA1 and BRCA2 breast cancers." (PMID 23704984, 2013). "In this work, we report the biological effects of cucurbitacin B extracted from medicinal herb Trichosanthes cucumerina L., on human breast cancer cells with or without functional BRCA1." (PMID 23393598, 2013). "Immunohistochemical analysis indicated that PTEN and BRCA1 are downregulated in 47% and 77.8% of metastatic breast cancer tissues, respectively, and the levels of PTEN and BRCA1 were both negatively correlated with the miR-20b expression (r=−0.996 and −0.778, respectively)." (PMID 23945289, 2013). "Several studies have indicated that the genetic makeup of BRCA1 and BRCA2 mutation-related breast cancer is different from that of non-BRCA mutation-related breast cancer." (PMID 23409121, 2013).
breast cancer (continued). "When breast cancer cells were cultured in soft agar either with or without cucurbitacin B, clonal growth of the BRCA1 knocked-down cells was inhibited significantly in the presence of cucurbitacin B compared with the untreated control cells." (PMID 23393598, 2013). "In this study we have also identified 19 BRCA1 and 3 BRCA2 VUS that were predicted to alter known in vitro and in vivo phosphorylated sites, however, not yet characterized for their biological role in protein function or in breast cancer development." (PMID 23704879, 2013). "We found variable BRCA1 protein immunostaining in tumor cell nuclei in frozen tissue sections with the AP16 and K-18 antibodies and with the MS110 antibody in contiguous FFPE tissues of randomly selected breast carcinomas." (PMID 23855721, 2013). "The great fraction of BRCA1-positive breast cancers without family history described in our study confirms previous observations reported in Polish and other populations." (PMID 22395474, 2012). "Compared with noncarriers, BRCA1 and BRCA2 mutation carriers have a substantially increased lifetime risk of contralateral breast cancer that is age dependent and can be up to 68%, if the age of the first cancer is <40." (PMID 22838957, 2012). "The present study evaluated the prevalence of BRCA1 and BRCA2 mutations in the second KOHBRA group, breast cancer patients without family history of breast or ovarian cancer with other risk factors for genetic predisposition." (PMID 22382806, 2012). "Overall 43 mutations (18 BRCA1 genes and 25 BRCA2 genes) were identified in high-risk breast cancer patients without a family history of breast or ovarian cancer." (PMID 22382806, 2012). "In the case of the Triple-Negative derived BRCA1/BRCA2-deficient breast cancers, poly(ADP-ribose) polymerase (PARP), with or without DNA damaging agents, is synthetic lethal with BRCA1- or BRCA2-deficiency." (PMID 22363779, 2012). "The coding region of the RAD51D gene was analysed in 175 BRCA1/2-negative families with family histories of both ovarian and breast cancer ascertained from two Canadian and two Belgian institutions." (PMID 22415235, 2012). "Overall mutation of BRCA1 and BRCA2 genes in high-risk breast cancer patients without family history of breast or ovarian cancer in this study was 8.6% (BRCA1: 3.3%, BRCA2: 5.3%)." (PMID 22382806, 2012). "The importance of the BRCA1 multi-protein complex has been exemplified by the identification of polymorphisms and haplotypes within other BRCA1 complex members, such as RAP80 and ABRAXAS, both in BRCA1/2 mutated and non-mutated familial breast cancer patients." (PMID 22706632, 2012). "In conclusion, BRCA1 and BRCA2 mutations were detected at higher frequency than reported for Korean sporadic breast cancer patients in those patients with no family history of breast or ovarian cancer but with other risk factors of genetic disease." (PMID 22382806, 2012). "Comparison of methylation profiles of the 12 breast cancer candidate genes in the paired lymph node metastasis to the matched normal tissue showed significantly higher methylation levels for APC, BMP6, BRCA1 and P16 genes (P < 0.05 and P < 0.01, P < 0.0001, P < 0.05; respectively)." (PMID 22695536, 2012). "In 21 out of 55 (38%) BRCA1-positive breast cancer cases no case of breast and/or ovarian cancer was observed in first- or second-degree relatives." (PMID 22395474, 2012). "Nonetheless, for women without mutations in BRCA1 or BRCA2, family history remains a strong predictive risk factor for breast cancer." (PMID 22703186, 2012). "Among 285 female probands, most were breast cancer patients (98%), and 247 (86.7%), 15 (5.3%), and 23 (8.1%) were noncarriers, BRCA1, and BRCA2 carriers respectively." (PMID 22290208, 2012). "BRCA1/p220-assocaited and triple negative/basal-like (TN/BL) tumors are aggressive and incurable breast cancer diseases that share among other features the no/low BRCA1/p220 expression." (PMID 22431556, 2012).